INS (insulin)
Diseases named in the same sentence as INS in open-access papers (continued):
Sharing a sentence is not in itself a finding about the gene and the disease.
Hypoglycemia (continued). "Laboratories consistent with excess insulin action include suppressed beta-hydroxybutyrate and free fatty acid concentrations as well as an inappropriate glycemic response to glucagon of 30 mg/dL or more at the time of hypoglycemia." (PMID 23384201, 2013). "Intriguingly, this is a potentially analogous situation in which autoantibodies against insulin may play a role in the shifts of bioavailable levels of insulin with possible effects on hypoglycemia." (PMID 24106499, 2013). "Further, P1736 did not cause hypoglycemia in treated animals, confirming its mode of action as an insulin sensitizer." (PMID 24194903, 2013). "The DPP-4 inhibitors promote glucose-dependent insulin secretion, i.e., in the presence of lower blood glucose values, the insulin release is not expected, which contributes to reduce the risk of hypoglycemia." (PMID 23697612, 2013). "Eight patients experienced hypoglycemia secondary to either oral antidiabetic drugs or insulin." (PMID 23289895, 2013). "Preserving functional β-cell mass and stimulating endogenous insulin secretion without causing hypoglycemia are the goals in the development of novel anti-diabetic drugs." (PMID 24386218, 2013). "We previously showed that insulin-hypoglycemia increases VMH NO production." (PMID 23894333, 2013). "A recent study showed Radix astragali, which is one of the TCM components of Xiaoke Pill, could amplify the glucose counter-regulatory response to insulin-induced hypoglycemia in rats." (PMID 23460810, 2013). "Insulin levels during euglycemia were 160±4 vs 159±5 during hypoglycemia (p = 0.6)." (PMID 23555895, 2013). "However, intensive insulin therapy, essential for type 1 diabetic patients and some of those with type 2, has insulin-induced hypoglycemia (IIH) as its major adverse effect." (PMID 24062772, 2013). "Brain glycogen decreases upon insulin-induced hypoglycemia due to enhanced glycogenolysis rate." (PMID 24194729, 2013). "We therefore hypothesized that pyruvate may be able to improve the outcome in diabetic rats subjected to insulin-induced R/M hypoglycemia by terminating hypoglycemia with glucose plus pyruvate, as compared with delivering just glucose alone." (PMID 24278448, 2013). "Having done a radioembolization to liver metastases, we thought that the primary tumour was still a significant source of endogenous insulin and decided to irradiate it externally since we wanted to be sure that she would be free of hypoglycemia episodes after discharge." (PMID 23738155, 2013). "Finally, several studies have also shown a lower occurrence of hypoglycemia with the use of rapid-acting insulin analogues." (PMID 24244557, 2013). "Patients receiving intensive insulin therapy are at increased risk of hypoglycemia despite lack of other risk factors." (PMID 23497433, 2012). "However, hypoglycemia (<40 mg/dL) is found only in a minority of patients (less than 40% of cases) while inappropriate secretion of insulin is present in a higher percentage of patients." (PMID 24213321, 2012). "However, from animal studies it is known that insulin-induced hypoglycemia detected in the portal vein is mediated through spinal sympathetic afferents and subsequently suppressed by sympathectomy." (PMID 22395951, 2012). "This pathway may also provide a mechanistic explanation, at least in part, for hypoglycemia occurring in insulin-treated type 1 diabetic patients." (PMID 23316165, 2012). "We found that the incidence of hypoglycemia was markedly increased by intensive insulin therapy." (PMID 23082798, 2012). "When hypoglycemia happens, a decrease in insulin secretion is the first response." (PMID 23497433, 2012). "While confirmation of insulin poisoning requires serum insulin and C-peptide concentrations, the first suspicion may be raised by the occurrence of unexplained hypoglycemia." (PMID 22768352, 2012).
Hypoglycemia (continued). "In addition, glucose and insulin tolerance tests revealed hypoglycemia and profoundly increased peripheral insulin sensitivity in Kl−/− mice." (PMID 22319626, 2012). "Moreover, the mutant mice also displayed enhanced glucose tolerance and elevated insulin sensitivity as a result of increased insulin signaling, ultimately resulting in disturbed glucose homeostasis and hypoglycemia." (PMID 23077600, 2012). "Additionally, SMBG makes patients feel more secure and comfortable using insulin since it allows early recognition of symptoms of hypoglycemia." (PMID 23259688, 2012). "However, 9 months after gastric bypass, she began experiencing frequent episodes of hypoglycemia, which persisted despite discontinuation of insulin and modification of her diet." (PMID 22937294, 2012). "Hypoglycemia in patients without diabetes has many potential causes, one of which is the malicious administration of insulin." (PMID 22768352, 2012). "It has been noted that children with postprandial HH after Nissen’s fundoplication have abnormally exaggerated secretion of glucagon-like peptide-1 (GLP-1), which may contribute to the exaggerated insulin surge and resultant hypoglycaemia." (PMID 23032149, 2012). "Although she had no definite episode of adrenal insufficiency, longitudinal data showed that her blood cortisol peak, after stimulation by hypoglycemia with insulin tolerance tests, decreased gradually with age (20.5, 17.5, 16.4, and 10.0 μg/dL, at ages of 5, 13, 14, and 15 years, respectively, Ref." (PMID 23029363, 2012). "A meta-analysis study showed that intensive insulin therapy has no advantage in reducing the mortality rate, but significantly increases the risk of hypoglycemia." (PMID 22480187, 2012). "When we examined the use of TZD in conjunction with sulfonylureas and insulin (two of the most commonly used medications in ACCORD), we found the highest rates of hypoglycemia among those who were prescribed TZDs in combination with insulin as compared to the combination of TZD with sulfonylureas." (PMID 22646230, 2012). "However, in the analogue group the incidence of severe hypoglycaemia ranged from 0–247 (median 22) episodes per 100 patient-year compared to the incidence in the human insulin group ranging from 0–544 (median 46)." (PMID 22727048, 2012). "However, they experience significant practical and often emotional challenges due to repeated blood glucose measurements and administration of insulin, fear of hypoglycaemia, ketoacidosis and long term complications on a daily basis." (PMID 22300248, 2012). "The HypoAna Trial is designed to investigate whether short-acting and long-acting insulin analogues in comparison with human insulin are superior in reducing the occurrence of severe hypoglycaemic episodes in patients with recurrent hypoglycaemia." (PMID 22727048, 2012). "The degree of metabolic control (as measured through glycated hemoglobin) that can be obtained with NPH human insulin is not improved by the use of glargine, the only advantage being a lower risk of hypoglycemia." (PMID 23209929, 2012). "Daily insulin dose was adjusted around 20 to 25 IU/kg/d to maintain the blood glucose of GK at the range of 4 to 6 mmol/L for 20 days, with one GK out of eight died of hypoglycemia." (PMID 21977022, 2012). "Insulin discontinuation when blood glucose was below 90 mg/dL also could explain in part the low rate of hypoglycemia that we observed." (PMID 22697362, 2012). "Secondary outcomes include evaluating factors associated with glycemic control, hypoglycemia, and treatment adherence among patients who do and do not progress beyond their initial insulin therapy and exploring geographic heterogeneity in treatment." (PMID 22999494, 2012). "Hypoglycemia results from IGF II action through insulin or IGF I receptors." (PMID 23056056, 2012). "The final stage of intensification may require prandial insulin, adding complexity and increased risks of hypoglycaemia and weight gain." (PMID 23061886, 2012).
Hypoglycemia (continued). "Overall, the elevated insulin sensitivity and the resulting persistant hypoglycemia might contribute to postnatal lethality of the knockout mice." (PMID 23077600, 2012). "The insulin autoimmune syndrome (IAS, Hirata disease) is characterized by a combination of fasting and sometimes postprandial hypoglycemia, high serum concentrations of total immunoreactive insulin, and presence in the serum of polyclonal autoantibodies against native human insulin." (PMID 22567309, 2012). "Thus, those symptoms should be alleviated upon increased insulin levels, accomplished by exogenous insulin plus glucose administration (to maintain euglycemia, avoiding the deleterious effects of hypoglycemia on memory and cognition)." (PMID 22500228, 2012). "Instantaneous readings may not result in improved glycemic control and may accentuate the frequency of hypoglycemia because of the delay in the insulin response." (PMID 23209941, 2012). "This methodology could be utilized in a future randomized controlled trial to assess the efficacy of insulin infusions for glucose control whilst avoiding the complication of increased rates of hypoglycemia in the tightly controlled group." (PMID 22871230, 2012). "The effect of insulin analogues on glycaemic control has been documented in large trials, while their effect on the frequency of severe hypoglycaemia is less clear, especially in patients with recurrent severe hypoglycaemia." (PMID 22727048, 2012). "Key contributors to treatment non-adherence are fear of hypoglycaemia, difficulty and lack of self-efficacy associated with insulin dose determination." (PMID 23062116, 2012). "Hypoglycemia occurring during IIT has been associated with severity score, ICU length of stay, outcome, inotropic support hemodialysis, and errors in administering insulin." (PMID 22697362, 2012). "However, the occurrence of severe hypoglycaemia was rare, even with intensive insulin therapy targeting fasting plasma glucose < 5.6 mmol/l." (PMID 22413808, 2012). "However, larger trials of insulin usage in both neonates and adults have been confounded by increased rates of hypoglycemia." (PMID 22871230, 2012). "Some early studies showed that an intake of 50–75 g of rapidly absorbable carbohydrate in a fasted state and shortly prior to exercise induced a rapid rise in blood glucose and insulin followed by a rebound hypoglycaemia as well as decreased performance during the subsequent exercise." (PMID 22780564, 2012). "Those participants treated with insulin plus oral medication had a rate of hypoglycemia that was between those treated with only oral agents and those treated with insulin alone, 3.31 to 3.69 per 100 person years in the intensive and 1.60-1.85 per 100 person years in the standard group." (PMID 22646230, 2012). "The rate of severe hypoglycemia in the intensive insulin therapy ranged from 5.1 to 28.6%." (PMID 22480187, 2012). "In summary, we reviewed different treatment options for postprandial hypoglycemia in dumping syndrome and report the novel use of aspart insulin as an alternative treatment in those who fail, are unable to tolerate, or want to avoid the other proposed treatment modalities." (PMID 22937294, 2012). "In contrast to agents that promote insulin secretion via glucose-independent mechanisms, the dependence of GLP-1 on glucose concentration is considered a unique safety advantage due to a lower risk of hypoglycemia." (PMID 23554750, 2012). "With regard to the safety of insulin glargine use during pregnancy, in comparison to NPH insulin, there was no increased risk to the mother for weight gain, severe hypoglycemia, gestational/new-onset hypertension, preeclampsia, or cesarean section." (PMID 22685467, 2012). "Intensive insulin therapy significantly increases the risk of hypoglycemia and does not influence mortality among neurocritical care patients." (PMID 23082798, 2012).
Hypoglycemia (continued). "Consistent with this proposed treatment algorithm, the frequency of recent hypoglycemia in CHOICE was numerically higher in patients who initiated exenatide b.i.d. than in the insulin cohort, but the number of affected patients was small and the difference was not statistically significant." (PMID 22714818, 2012). "The recent guidelines suggest that a mixed meal (recreating if possible the circumstances of hypoglycaemia) is indicated with the following measurements done at baseline and every 30 min for 5 h: blood glucose level, insulin, C-peptide, proinsulin, beta hydroxybutyrate, sulfamide and repaglinide." (PMID 22587661, 2012). "In addition, OB mitral cell reactivity is increased by short-term starvation and insulin-induced hypoglycemia and decreased by re-feeding and gastric distension." (PMID 23251461, 2012). "NPH insulin should be reduced by one-half or one-third prior to surgery to avoid hypoglycemia." (PMID 23209941, 2012). "Amongst patients receiving any type of monotherapy, insulin use was the only positive predictor of incident hypoglycaemia (OR 6.59; 95%CI 4.43-9.79) while the reduced rate with DPP-4 inhibitors was statistically only borderline significant (OR 0.52; 95%CI 0.26-1.03)." (PMID 23075070, 2012). "Insulin secretion from β-cells is precisely regulated by various mechanisms to maintain blood glucose values within the normal range (fasting blood glucose leSymptoms of hypoglycaemia can either be seen during fasting, or after a provels of 3.5–5.5 mmol/L)." (PMID 23032149, 2012). "However, for several reasons the impact of insulin analogues on the frequency of severe hypoglycaemia is less clear." (PMID 22727048, 2012). "The hypoglycemic episodes were significantly correlated with 2-h post-load plasma glucose and insulin levels, thus raising the possibility that hypoglycemia occurs during the late post-prandial period as a consequence of a prolonged release of insulin in response to elevated glucose levels." (PMID 22164268, 2011). "TMK could treat T2DM and could reduce hypoglycemia and the dose of insulin at the base of controlled blood glucose." (PMID 21584252, 2011). "Another challenge with exogenous insulin administration is hypoglycemia." (PMID 22067102, 2011). "Individuals and clinicians may experience difficulties in optimizing multiple insulin doses while avoiding hypoglycaemia thereby necessitating frequent self-monitoring of blood glucose." (PMID 21679291, 2011). "The vast majority of hypoglycemia is due to issues with insulin dosing." (PMID 23882328, 2011). "Such a protocol may include an extension of the protocol described in Section 2.4 wherein a period of slight hypoglycaemia is achieved for each participant with a series of participant-specific insulin boluses administered with feed-back control." (PMID 21615928, 2011). "Our data suggest that the hypoglycemia observed in ERRα-null mice under ad libitum feeding may in part be due to enhanced insulin secretion and/or response." (PMID 21731503, 2011). "Hypoglycemia can be a side effect of intensive insulin therapy." (PMID 22067102, 2011). "In addition to fasting, ghrelin expression can be stimulated in rats by means of insulin-induced hypoglycemia, and some observations indicate a direct inhibitory effect of glucose on ghrelin-containing cells in the oxyntic mucosa." (PMID 21999723, 2011). "Less frequent episodes of hypoglycemia may also result in less weight gain that can be seen in intensive insulin therapy." (PMID 22067102, 2011). "In addition, the ERRα-null mice exhibit time-dependent hypoglycemia and hypoinsulinemia, suggesting a role for ERRα in modulating insulin sensitivity and glucose handling during the 24-hour light/dark cycle." (PMID 21731503, 2011). "In these subjects, a persistent increase in insulin levels after a meal may result in late postprandial hypoglycemia." (PMID 22164268, 2011).
Hypoglycemia (continued). "However, adequate control of circulating glucose levels cannot be attained by most patients, and attempts at maintaining euglycemia through intensive insulin therapy lead to hypoglycemia." (PMID 21234246, 2011). "The main clinical symptom in insulinoma patients is the inability to suppress insulin secretion in the presence of hypoglycaemia, resulting in neuroglycopenia and adrenergic manifestations like headache, confusion, visual troubles, shivering, irritability and palpitations." (PMID 21266045, 2011). "We thus hypothesize that the observed hypoglycemia in ERRα-null mice is a result of enhanced glucose uptake due to increased insulin sensitivity." (PMID 21731503, 2011). "GLP-1 actions are highly glucose-dependent, hence GLP-1 administration is unlikely to be associated with hypoglycemia, a frequent side effect of many oral anti-diabetic agents and insulin." (PMID 21673955, 2011). "The simplest approach to reduce severity of hypoglycemia is to interrupt insulin delivery." (PMID 22071283, 2011). "Moreover, insulin inhibits lipolysis, thus preventing compensatory ketogenesis to protect the brain from hypoglycemia." (PMID 21967988, 2011). "Thus, if hypoglycemias are still occurring despite higher glucose infusion rate, the only possible mechanism is insulin." (PMID 21967988, 2011). "Moreover, in vivo studies recently showed production of mitochondrial RS in newborn brain during acute hypoglycemia and in insulin-induced hypoglycemic stress in healthy subject." (PMID 21738719, 2011). "We hypothesize that this was likely physiologic and in response to hypoglycemia induced by administration of insulin." (PMID 22214514, 2011). "Enhancing the pharmacological predictability and extending the duration of action could simplify insulin titration and further reduce the incidence of hypoglycaemia." (PMID 21410860, 2011). "- The question has not been finally answered whether the therapy with long-acting insulin analogues predominantly affects frequency of hypoglycaemia or predominantly affects metabolic control." (PMID 21978524, 2011). "However, discrepancies with regard to time of onset of hypoglycemia and plasma insulin levels have been published." (PMID 20936117, 2010). "For example, insulin-induced hypoglycemia increases brain ROS levels." (PMID 22022208, 2010). "In peripheral tissues, insulin is rightly considered as the anabolic hormone: insulin injections induce hypoglycemia with a temporary increase in food intake as a consequence and it will promote fuel storage in peripheral organs, mainly in liver and adipose tissues." (PMID 20976162, 2010). "Heart rate correction may also influence the QT during hypoglycemia while the type of insulin is insignificant." (PMID 21234404, 2010). "The rate of severe hypoglycemia is lower with both basal insulin analogues." (PMID 20589066, 2010). "The authors speculated that patients tend to reduce their insulin dosage to prevent exercise induced hypoglycemia." (PMID 20618996, 2010). "Moreover, injection of exogenous insulin to CR mice leads to severe hypoglycemia which can result in death." (PMID 20307313, 2010). "We recommend including in a glucose control protocol, at the very least, recommendations on the use of rapid action insulin as a continuous infusion by electric syringe pump, as well as on correction and monitoring procedures for episodes of hypoglycemia (strong agreement)." (PMID 20840773, 2010). "Yet, it should be appreciated that the absolute frequency of severe hypoglycaemia may be lower with the use of analogue insulin therapy." (PMID 20456170, 2010). "Prospective analysis is required to assess the influence of insulin at pre-defined blood and brain glucose levels with the aim of identifying potentially deleterious episodes possibly related to relative and even individual thresholds of hypoglycemia." (PMID 20141631, 2010).